GGPS1 (geranylgeranyl diphosphate synthase 1)
Description:
Catalyzes the trans-addition of the three molecules of IPP onto DMAPP to form geranylgeranyl pyrophosphate, an important precursor of carotenoids and geranylated proteins.
Synonyms: GGPPS1; GGPPS; MDHLO; MUDHLOV
Tractability: Small molecule: a structure with a bound ligand is known; a high-quality ligand is known; it has a binding pocket of medium quality; it belongs to a druggable protein family. PROTAC: ubiquitination databases record sites on it; its protein half-life has been measured; a small molecule that binds it is known.
Target class: Enzyme; Transferase
Gene: Protein-coding gene on chromosome 1 (235,327,350 to 235,344,532, forward strand). Ensembl gene ENSG00000152904.
Subcellular location: Cytoplasm; Cytoplasm, perinuclear region; Cytoplasm, myofibril, sarcomere, Z line
Subcellular location (Human Protein Atlas): Cytosol; Nucleoplasm
Pathways (Reactome):
Metabolism: Activation of gene expression by SREBF (SREBP); Lanosterol biosynthesis
Gene Ontology:
Molecular function: geranylgeranyl diphosphate synthase activity; identical protein binding; protein binding; (2E,6E)-farnesyl diphosphate synthase activity; dimethylallyltranstransferase activity; prenyltransferase activity
Biological process: isoprenoid metabolic process; isoprenoid biosynthetic process; farnesyl diphosphate biosynthetic process; geranyl diphosphate biosynthetic process; geranylgeranyl diphosphate biosynthetic process
Cellular component: cytoplasm; cytosol; perinuclear region of cytoplasm; Z disc
Genetic constraint (gnomAD): Loss-of-function variants: 7 observed, 12.95 expected, observed/expected ratio (o/e) 0.54, 90% interval 0.31 to 1.02. The upper end of that interval is the gene's LOEUF score, 1.02, which puts it in group 4 of 6, group 1 being the genes least tolerant of losing a copy. Missense variants: 143 observed, 196.98 expected, observed/expected ratio (o/e) 0.73, 90% interval 0.63 to 0.83. Synonymous variants: 74 observed, 74.52 expected, observed/expected ratio (o/e) 0.99, 90% interval 0.82 to 1.21.
Homologues: Orthologues: chimpanzee GGPS1 (100% identical), macaque GGPS1 (99% identical), pig GGPS1 (99% identical), rabbit GGPS1 (99% identical), dog GGPS1 (98% identical), guinea pig GGPS1 (95% identical), mouse Ggps1 (94% identical), rat Ggps1 (89% identical), zebrafish ggps1 (83% identical), Drosophila melanogaster qm (58% identical). Paralogues in human: PDSS1 (21% identical), PDSS2 (17% identical).
Diseases named in the same sentence as GGPS1 in open-access papers:
GGPS1 is named in the same sentence as 72 diseases in open-access papers, as found by Europe PMC text mining. Sharing a sentence is not in itself a finding about the gene and the disease. The quoted sentences say what the papers report.
muscular dystrophy (5 papers, 2022 to 2025). Muscular dystrophy (MD) refers to a group of more than 30 genetic diseases characterized by progressive weakness and degeneration of the skeletal muscles that control movement. "Research has revealed that GGPS1 mutations cause muscular dystrophy, hearing loss, and ovarian insufficiency syndrome in patients." (PMID 37611828, 2023). "Ultra‐rare biallelic pathogenic variants in geranylgeranyl diphosphate synthase 1 (GGPS1) have recently been associated with muscular dystrophy/hearing loss/ovarian insufficiency syndrome." (PMID 35869884, 2022). "Missense mutations in GGPS1 defined a syndrome of muscular dystrophy." (PMID 38473071, 2024). "This could suggest that hearing loss might be a variable feature of GGPS1‐associated muscular dystrophy and is an interesting observation in light of its diffuse expression in the embryonic and postnatal mouse inner ear." (PMID 35869884, 2022). "Among the participants with muscular dystrophy, four were diagnosed with Steinert’s disease, two with facioscapulohumeral dystrophy, three with Emery-Dreifuss muscular dystrophy, three with limb-girdle muscular dystrophy, and one with muscular dystrophy due to a GGPS1 mutation." (PMID 40638490, 2025). "Ggps1 is also involved in muscular dystrophy and promotes rab37-mediated autophagy." (PMID 39156629, 2024). "The individual's phenotype was felt to be highly specific for GGPS1 related muscular dystrophy." (PMID 35869884, 2022).
hepatocellular carcinoma (4 papers, 2014 to 2025). A malignant tumor that arises from hepatocytes. "GGPS1 is a member of the prenyltransferase family and acts as an enzyme for the posttranslational modification of proteins, has key roles in signalling pathways like cytoskeletal regulation and intracellular transport and can serve as a biomarker in Hepatocellular carcinoma." (PMID 40535577, 2025).
lung adenocarcinoma (4 papers, 2018 to 2024). A carcinoma that arises from the lung and is characterized by the presence of malignant glandular epithelial cells. "In consistent with these findings, we found that Ggps1 mRNA expression was significantly higher in lung adenocarcinoma tissues than in adjacent normal tissues (P < 0.001)." (PMID 29377583, 2018). "Expression levels of the GGPS1 and PMVK genes were only significantly correlated with HMGA1 expression in lung adenocarcinoma." (PMID 35805937, 2022).
multiple myeloma (4 papers, 2021 to 2025). "The noted upregulation of GGPS1 and FDPS is an important observation in the context of breast cancer pathogenesis as these enzymes are components of the mevalonate pathway with role in cholesterol biosynthesis and bone metastasis of breast cancer, prostate cancer, and multiple myeloma." (PMID 33670680, 2021).
hearing loss (3 papers, 2022 to 2024). "In addition, a pathogenic GGPS1 variant was identified in one family with muscle dystrophy, hearing loss, and ovarian insufficiency syndrome, suggesting an impairment in geranylgeranylation of small GTPases with multisystemic effects." (PMID 38982518, 2024).
lung carcinoma (3 papers, 2018 to 2022). "Our findings indicate that the MVK, GGPS1 and PMVK expression was correlated with HMGA1 gene expression in lung cancer tissues, but not in normal lung tissue." (PMID 35805937, 2022).
ovarian carcinoma (3 papers, 2020 to 2024). A malignant neoplasm originating from the surface ovarian epithelium. "A metabolic pathway was the most significant pathway enriched by GGPS1, ME1, DSE, NTPCR, PPOX, and PC.ME1 and DSE have been reported to be associated with the development of ovarian cancer in previous studies." (PMID 33177242, 2020). "Similarly, the overexpression of GGPS1, GART, and HMGCS1 reduced the overall survival duration in patients with glioblastoma, ovarian cancer, and endometrial cancer but not in those with prostate cancer." (PMID 33670680, 2021).
breast carcinoma (2 papers, 2018 to 2021). "To exemplify the usefulness of the findings presented here, we focused on breast cancer and demonstrate that targets of bisphosphonates such as FDPS and GGPS1 as well as statin such as HMGCS1 are excellent fitness genes in breast cancer and many hard-to-treat cancers." (PMID 33670680, 2021). "However, the nature and context of cellular targets of bisphosphonates in breast cancer (GGPS1 and FDPS) are expected to be different from its targets in bone." (PMID 33670680, 2021). "GGPS1, FDPS, and GART are upregulated in multiple cancers in addition to breast cancer (also TNBC), including hard-to-treat cancers such as esophageal, pancreatic, lung, and oral cancers and glioblastoma." (PMID 33670680, 2021). "The significance of the overexpression of GGPS1, FDPS, and GART in the pathophysiology of breast cancer is also evident by the fitness dependency of breast cancer cells on these genes." (PMID 33670680, 2021). "The overexpression of GGPS1, FDPS, and GART in breast cancer was also associated with a highly significant overall reduction in the survival of patients with breast cancer compared with that of patients without overexpression of these cellular molecules." (PMID 33670680, 2021). "GGPS1 and FDPS are targets of nitrogen-containing bisphosphonates such as zoledronic acid derivatives that are widely used to prevent bone-related events related to breast cancer relapse." (PMID 33670680, 2021). "The levels of GGPS1, FDPS, and GART were significantly elevated in breast tumors as compared to matching adjacent normal tissues, breast cancer cell lines, breast cancer subtypes, and triple negative breast cancer (TNBC) compared with the normal adjacent tissue or non-TNBC tumors." (PMID 33670680, 2021).
esophageal cancer (2 papers, 2021 to 2024). A primary or metastatic malignant neoplasm involving the esophagus. "In oral and esophageal cancer, it reduces cancer cell growth through suppressing MET signaling by regulating geranylgeranyl diphosphate synthase 1 expression." (PMID 38319449, 2024).
infertile (2 papers, 2019 to 2023). "Decreased GGPS1 expression in the testis has also been associated with infertility in men, suggesting a role for this enzyme in both male and female reproductive organs." (PMID 36650113, 2023). "However, this has not been confirmed since most females with GGPS1 mutations suffer from primary ovarian insufficiency and infertility." (PMID 36650113, 2023).
leukemia (2 papers, 2015 to 2017). A malignant (clonal) hematologic disorder, involving hematopoietic stem cells and characterized by the presence of primitive or atypical myeloid or lymphoid cells in the bone marrow and the blood. "Moreover, recent results demonstrate dramatic synergy of pharmacological GGPS1 inhibitors was evident when combined with statins at inducing leukemia cell kill." (PMID 26353928, 2015).
ovarian insufficiency (2 papers, 2022 to 2023). "All postpubertal females had primary ovarian insufficiency, which is consistent with the findings of our genetic work in an animal model revealing that GGPS1 is essential for early folliculogenesis and oocyte maturation in women fertility." (PMID 37611828, 2023).
Perrault syndrome (2 papers, 2023 to 2024). Perrault syndrome (PS) is characterized by the association of ovarian dysgenesis in females with sensorineural hearing impairment. "In addition to well-established Perrault syndrome genes involved in mitochondrial function, recent studies have described causative variants in non-mitochondrial genes including HSD17B4, GGPS1 and PEX6 in patients presenting with clinical features overlapping with Perrault syndrome." (PMID 37148394, 2023).
Ataxia (1 paper, 2023). Ataxia refers to impaired coordination of voluntary muscle movement. "We report that conditional knockout (cKO) of Ggps1 leads to severe ataxia and deficient locomotion." (PMID 36782228, 2023).
breast tumors (1 paper, 2021). "The overexpression of GGPS1, FDPS, and GART mRNAs and their respective proteins was observed in breast tumors, along with the coexpression of GGPS1, FDPS, and GART proteins in several of the same breast tumors (presented as empty blocks)." (PMID 33670680, 2021). "We noticed an inverse relationship between levels of MAF upregulation and those of GGPS1 or FDPS, and an almost exclusive expression of MAF and GGPS1 or MAF and FDPS in breast tumors." (PMID 33670680, 2021). "Among these cell fitness molecules, we observed a widespread mRNA overexpression and copy number amplification of Geranylgeranyl pyrophosphate synthase (GGPS1), Farnesyl diphosphate synthase (FDPS), and GART (also known as glycinamide ribonucleotide formyl transferase—(GARFT) in breast tumors." (PMID 33670680, 2021).
CNS cancers (1 paper, 2021). "We also observed that the overexpression of HMGCS1, GGPS1, FDPS, and GART in breast, ovarian, endometrial, pancreatic, and CNS cancers correlated well with a reduction in the overall survival of patients when compared with that of patients without overexpression of these genes." (PMID 33670680, 2021).
congenital myopathies (1 paper, 2025). "GGPP depletion has also been shown to regulate MSTN and cause skeletal muscle atrophy in mice, and mutations in GGPS1, encoding a GGPP synthase, have been linked to congenital myopathies." (PMID 41373724, 2025).
dystocia (1 paper, 2023). Slow or difficult obstetric labor or childbirth. "Furthermore, a different study found in Geranylgeranyl pyrophosphate synthase (Ggps1)-KO mice that 75% of all pregnancies ended with dystocia." (PMID 38069145, 2023).
gastric cancer (1 paper, 2022). A primary or metastatic malignant neoplasm involving the stomach. "Only the B cell score of the GGPS1 gene was significant in gastric cancer." (PMID 36140749, 2022).
oral squamous cell carcinoma (1 paper, 2023). "All in all, this study aimed to better understand the prognosis of oral squamous cell carcinoma related to GGPS1 expression and the function of the GGPS1, so as to broaden the scope of diagnostic and prognostic indicators for OSCC." (PMID 37033446, 2023).
osteoporosis (1 paper, 2019). A condition of reduced bone mass, with decreased cortical thickness and a decrease in the number and size of the trabeculae of cancellous bone (but normal chemical composition), resulting in increased fracture incidence. "At the same time, it is worth noting that in previously published studies the ambiguous results of the association of FDPS and GGPS1 gene variants with antiresorptive therapy of osteoporosis were obtained." (PMID 31437227, 2019). "In conclusion, we reported for the first time the importance of identified allelic combinations of SOST rs1234612, PTH rs7125774, FDPS rs2297480, and GGPS1 rs10925503 gene variants for evaluation of the individual resistance or sensitivity to BPs treatment of osteoporosis." (PMID 31437227, 2019).
pancreatic cancers (1 paper, 2021). "Additionally, the overexpression of GGPS1, FDPS, GART, and 3-hydroxy-3-methylglutaryl-CoA synthase 1 (HMGCS1) was also associated with a highly significant overall reduction in the survival duration of patients with esophageal and pancreatic cancers." (PMID 33670680, 2021).
postmenopausal osteoporosis (1 paper, 2019). Metabolic disorder associated with fractures of the femoral neck, vertebrae, and distal forearm. "The results of this study show the possible role of allelic combinations of SOST rs1234612, PTH rs7125774, FDPS rs2297480, and GGPS1 rs10925503 gene variants in the individual response to BPs treatment in women with postmenopausal osteoporosis." (PMID 31437227, 2019).
prostate carcinoma (1 paper, 2021). A carcinoma that arises from epithelial cells of the prostate gland. "GGPS1 did not exhibit any fitness dependency in prostate cancer cells, whereas FDPS and GART had no fitness values." (PMID 33670680, 2021). "We found that the levels of GGPS1, FDPS, and GART were not upregulated in prostate cancer." (PMID 33670680, 2021).
cancer (13 papers, 2018 to 2025). A tumor composed of atypical neoplastic, often pleomorphic cells that invade other tissues. "Long-term statin use can cause cancer cells to upregulate key enzymes such as HMGCR or GGPP synthase (GGPS1), enabling sufficient isoprenoid supply even when HMG-CoR is inhibited." (PMID 41450917, 2025). "At the same time, multivariate Cox regression analyses showed that GGPS1 could be an independent prognostic biomarker, and its gene expression level is closely related to the histological stage of cancer." (PMID 37033446, 2023). "The development of drugs targeting GGPS1 is crucial for the effective treatment of cancer patients." (PMID 37033446, 2023). "Thus, GGPS1 may affect the occurrence and development of tumors by influencing various metabolism and may be beneficial to the occurrence of cancer." (PMID 37033446, 2023). "Our study indicates upregulation of multiple genes that are particularly enzymes involved in cholesterol biosynthesis, i.e., GGPS1, SQLE, FDPS, HMGCS1, and HMGCR, which were also reported in distinct cancer models." (PMID 35050168, 2022).
tumor (10 papers, 2014 to 2025). "This study obtained RNA-seq data and clinical data from TCGA to identify the associations between GGPS1 and OSCC, concluding that GGPS1 expression was higher in tumor tissues and the high expression could portend a worse prognosis for OSCC." (PMID 37033446, 2023). "Related to OSCC, the authors found significantly higher expressions of GGPS1 in tumour tissues compared to normal oral tissues." (PMID 40535577, 2025). "In lung adenocarcinoma, the overexpression of GGPS1 contributes to tumor metastasis and is correlated with poor prognosis." (PMID 37033446, 2023). "The data of tumor samples were divided into two parts with a line of demarcation that was derived from the median expression level of GGPS1." (PMID 37033446, 2023). "Expressions of GGPS1 were analyzed and the result showed that the expressions of GGPS1 in tumor tissues were significantly higher in normal tissues." (PMID 37033446, 2023). "Thus, it is speculated that GGPS1 may affect the metabolism of the tumor through some mechanisms." (PMID 37033446, 2023). "HMGCS1, GGPS1 and SREBP2 knockdown, in concert with statin-mediated HMGCR inhibition, can robustly enhance tumor cell apoptosis." (PMID 26353928, 2015). "Secondly, we did not conduct any wet-lab experiments on GGPS1 expression in OSCC tumor tissues due to experimental constraints." (PMID 37033446, 2023). "To demonstrate increased activity of the MVA pathway in CSCs of CRC, we cultured tumor spheres and found significantly elevated protein and mRNA levels of key enzymes of the MVA pathway, including HMGCR, FDPS, GGPS1, and SQLE, in tumor spheroids compared to 2D adherent cultured cells." (PMID 32911743, 2020). "Our finding that knocking down GGPS1 potentiates fluvastatin- mediated HMGCR inhibition is consistent with previous results from us and others that this arm of the MVA pathway is functionally critical for statin-induced apoptosis of tumor cells." (PMID 26353928, 2015). "This inspires a novel model by which the statin-triggered feedback loop would restore the MVA end-products, but in the presence of GGPS1 inhibitors, this lethal vulnerability would not be rescued leading to tumor cell death." (PMID 26353928, 2015).
GGPS1 also shares sentences with these, for which no sentence is quoted: Insulin resistance (6 papers); Obesity (5); diabetes (3); hyperinsulinism (3); cardiac hypertrophy (2); heart failure (2); malaria (2); male infertility (2); oral cancer (2); acute lymphoblastic leukemia (1); acute myeloid leukemia (1); bacterial infection (1); blood cancer (1); bone disorder (1); cardiac diseases (1); cholestasis (1); Cirrhosis (1); colon cancer (1); congenital muscular dystrophy (1); COVID-19 (1); cyst (1); Emery-Dreifuss muscular dystrophy (1); endometrial cancer (1); Facioscapulohumeral dystrophy (1); fatty liver disease (1); glioblastoma (1); Hepatitis (1); Hyperinsulinemia (1); idiopathic pulmonary fibrosis (1); infection (1).
A further 16 diseases each share a sentence with GGPS1 in 1 paper.